MIR516A1 (microRNA 516a-1)
Synonyms: hsa-mir-516-1; hsa-mir-516a-1; MIRN516-1; MIRN516A-1; MIRN516A1; mir-516a-1
Gene: MicroRNA gene on chromosome 19 (53,756,741 to 53,756,830, forward strand). Ensembl gene ENSG00000207767.
Gene Ontology:
Biological process: miRNA-mediated post-transcriptional gene silencing
Homologues: Orthologues: chimpanzee ptr-mir-516a-1 (100% identical), macaque mml-mir-516a-1 (92% identical). Paralogues in human: MIR516A2 (99% identical), MIR516B1 (92% identical), MIR520C (89% identical), MIR518E (87% identical), MIR519C (87% identical), MIR518C (86% identical), MIR519A2 (86% identical), MIR520F (86% identical), MIR522 (86% identical), MIR518D (84% identical), MIR520E (84% identical), MIR523 (84% identical), and 12 more.